NOS2 (nitric oxide synthase 2)
Description:
Produces nitric oxide (NO) which is a messenger molecule with diverse functions throughout the body. In macrophages, NO mediates tumoricidal and bactericidal actions. Also has nitrosylase activity and mediates cysteine S-nitrosylation of cytoplasmic target proteins such PTGS2/COX2 (By similarity). As component of the iNOS-S100A8/9 transnitrosylase complex involved in the selective inflammatory stimulus-dependent S-nitrosylation of GAPDH on 'Cys-247' implicated in regulation of the GAIT complex activity and probably multiple targets including ANXA5, EZR, MSN and VIM. Involved in inflammation, enhances the synthesis of pro-inflammatory mediators such as IL6 and IL8.
Synonyms: HEP-NOS; iNOS; NOS2A; NOS
Tractability: Small molecule: a drug acting on it is in phase 2 or 3 trials; a structure with a bound ligand is known; a high-quality ligand is known; it has a high-quality binding pocket; it belongs to a druggable protein family. Antibody: its Gene Ontology location is reachable by antibodies, with medium confidence. PROTAC: UniProt records ubiquitination sites on it; ubiquitination databases record sites on it; a small molecule that binds it is known.
Target class: Enzyme
Chemical probes: CHEMBL1762473, CHEMBL522771, PD081211, PD081524, PD082676, PD082692, PD083260, PD084650, PD085046
Safety:
Unwanted effects reported when the protein is acted on. In parentheses: how it was acted on, where the effect was seen, and who reports it.
Toxic liver disease (source: ClinPGx)
Gene: Protein-coding gene on chromosome 17 (27,756,766 to 27,800,758, reverse strand). Ensembl gene ENSG00000007171.
Subcellular location: Cytoplasm, cytosol
Pathways (Reactome):
Immune System: Interleukin-4 and Interleukin-13 signaling; ROS and RNS production in phagocytes
Disease: Inhibition of nitric oxide production
Hemostasis: Nitric oxide stimulates guanylate cyclase
Protein localization: Peroxisomal protein import
Gene Ontology:
Molecular function: nitric-oxide synthase activity; protein binding; arginine binding; flavin adenine dinucleotide binding; FMN binding; heme binding; NADP binding; tetrahydrobiopterin binding; calmodulin binding; oxidoreductase activity; protein homodimerization activity
Biological process: defense response to bacterium; Fc-gamma receptor signaling pathway involved in phagocytosis; L-arginine catabolic process; negative regulation of gene expression; nitric oxide biosynthetic process; positive regulation of interleukin-6 production; positive regulation of interleukin-8 production; prostaglandin secretion; regulation of cytokine production involved in inflammatory response; regulation of insulin secretion; cell redox homeostasis; defense response to Gram-negative bacterium; inflammatory response; innate immune response in mucosa; negative regulation of blood pressure; peptidyl-cysteine S-nitrosylation; positive regulation of leukocyte mediated cytotoxicity; regulation of cellular respiration; response to bacterium; response to hormone; response to lipopolysaccharide; superoxide metabolic process; circadian rhythm; negative regulation of protein catabolic process
Cellular component: cytoplasm; cytosol; peroxisome; nucleoplasm; nucleus; peroxisomal matrix; plasma membrane; cortical cytoskeleton; perinuclear region of cytoplasm
Genetic constraint (gnomAD): Loss-of-function variants: 92 observed, 127.52 expected, observed/expected ratio (o/e) 0.72, 90% interval 0.61 to 0.86. The upper end of that interval is the gene's LOEUF score, 0.86, which puts it in group 3 of 6, group 1 being the genes least tolerant of losing a copy. Missense variants: 1,208 observed, 1,433.4 expected, observed/expected ratio (o/e) 0.84, 90% interval 0.8 to 0.88. Synonymous variants: 524 observed, 561.61 expected, observed/expected ratio (o/e) 0.93, 90% interval 0.87 to 1.
Homologues: Orthologues: chimpanzee NOS2 (99% identical), macaque NOS2 (95% identical), dog NOS2 (87% identical), pig NOS2 (87% identical), rabbit NOS2 (82% identical), guinea pig NOS2 (82% identical), mouse Nos2 (81% identical), rat Nos2 (80% identical), tropical clawed frog nos2 (64% identical), zebrafish nos2b (55% identical), zebrafish nos2a (55% identical). Paralogues in human: NOS1 (54% identical), NOS3 (50% identical), POR (18% identical), MTRR (16% identical), NDOR1 (14% identical).
Diseases named in the same sentence as NOS2 in open-access papers:
NOS2 is named in the same sentence as 405 diseases in open-access papers, as found by Europe PMC text mining. Sharing a sentence is not in itself a finding about the gene and the disease. The quoted sentences say what the papers report.
Sepsis (57 papers, 2005 to 2026). Sepsis is defined as life-threatening organ dysfunction caused by a dysregulated host response to infection. "A better microvascular responsiveness and a lower mortality during experimental sepsis induced by cecal ligation and puncture were reported in Nos2-deficient animals compared to control animals." (PMID 34769369, 2021). "Sustained NO production following NOS2 induction is associated with sepsis hyporesponsivity." (PMID 27445832, 2016). "Inducible NOS (NOS2) has also been linked to myocardial dysfunction of sepsis." (PMID 17996049, 2007). "In detail, the inducible NOS (iNOS/NOS2) is the enzyme responsible for the production of NO in sepsis in response to endotoxins, cytokines, and other mediators." (PMID 38474158, 2024). "NO production is increased by the expression of the enzyme nitric oxide synthase isoform 2 (NOS‐2) in the kidney during sepsis in response to inflammatory cytokines." (PMID 39438268, 2024). "In pathological conditions, NO is mainly derived from nitric oxide synthase (NOS-2), which has been previously shown to be an important mediator of organ injury in HS and also in other conditions such as sepsis." (PMID 38194181, 2024). "Osteopontin is a biomarker of sepsis in humans and reportedly acts through Stat1 degradation to inhibit Nos2 transcription." (PMID 33849979, 2021). "Remarkably, NOS1 stabilizes NOS2 activity and is important for sepsis survival and bacterial clearance." (PMID 30679708, 2019). "The promoter of the NOS2 gene, which is responsible for excessive NO production in sepsis in response to LPS, can be bound by several transcriptional factors, such as NF-κB, AP-1, and STAT-1." (PMID 29211014, 2017). "On cellular level, sepsis results in a cytokine-mediated induction of NOS2 in almost any cell type, but especially in macrophages." (PMID 25699985, 2015). "Historically, cytokine-induced NOS2 expression and consequential enhanced NO production were suggested to be key factors in the development of sepsis-induced acute hemodynamic changes and end-organ damage." (PMID 25699985, 2015). "Preservation of HPV during experimental sepsis was achieved by administration of reactive oxygen species scavengers, by inhibition of NOS-2 with subsequent NO production or inhibition of the soluble guanylate cyclase as a molecular target of NO." (PMID 26415503, 2015). "The inhibition of the excess NO formation by inhibiting NOS2 activity was therefore proposed as a treatment for endotoxic shock or sepsis in the past." (PMID 25699985, 2015). "Historically, excessive NO production by NOS2 was suggested to play an important role in the development of the key features of sepsis and endotoxemia, the systemic hypotension and vascular hyporeactivity to vasopressor agents." (PMID 25699985, 2015). "In patients with maxillary sinusitis and sepsis, nasal NO production was significantly reduced in the sinus epithelium compared to control patients, suggested to be the result of reduced NOS2 mRNA expression." (PMID 25699985, 2015). "For example, both Nos2−/− mice and iNOS-inhibited wild-type mice had decreased numbers of apoptotic alveolar and bronchiolar epithelial cells following sepsis." (PMID 26376777, 2015). "During sepsis, NOS2, a key enzyme catalyzing the dramatic increase in NO by LPS, plays an important role in the pathophysiology of endotoxemia and sepsis." (PMID 25501336, 2014). "The inducible NOS (iNOS/NOS2) is generally believed to be the high-capacity NO-producing enzyme in sepsis." (PMID 23397596, 2013). "Along with these changes, the mRNA levels of inflammatory mediators such as tumor necrosis factor-α (Tnf-α), chemokine ligand 2 (Ccl2), interleukin-6 (Il-6), interleukin-1β (Il-1β), and nitric oxide synthase 2 (Nos2) also demonstrated a marked elevation in the sepsis group." (PMID 38705396, 2024). "The promoter of the NOS2 gene is responsible for excessive NO production by LPS in sepsis." (PMID 33946374, 2021).
Sepsis (continued). "Additionally, excessive NO production during sepsis, which is mainly generated by NO synthase 2 (NOS2, also named inducible NO synthase) encoded by NOS2 gene, has been suggested to be one of the main factors leading to tissue injury induced by septic shock." (PMID 29211014, 2017). "Therefore, maintenance of NOS2 derived NO is essential during sepsis and endotoxemia as part of the host defense mechanism, as inhibition results in detrimental outcome, which will be discussed in Section 4.1." (PMID 25699985, 2015). "Furthermore, genetic ablation of NOS2 in mice exhibited a decrease mortality and enhanced microvasculature responsiveness in a cecal ligation and puncture induced sepsis model." (PMID 25699985, 2015). "With a large amount of data supporting a detrimental role for NOS2 in sepsis, it might be expected that NOS2 inhibition would result in additional survival benefit in NOS3−/− mice." (PMID 23397596, 2013). "Significant contribution by inducible NOS (NOS2) during this early phase of sepsis was excluded." (PMID 23397596, 2013). "Therefore, we believe that modulations in NOS enzymes activity during human sepsis need to be performed with great precautions based on the diverse outcome of the several experimental models and the previous detrimental outcome in human sepsis with NOS2 inhibition." (PMID 25699985, 2015). "Hypothetically, decreasing the arginine availability during sepsis may, therefore function as a protective mechanism to decrease excessive NO production by NOS2 and to regulate excessive adaptive (T-lymphocyte) immune responses, preventing possible excessive inflammation during sepsis." (PMID 25699985, 2015). "Therefore, it is suggested that the upregulation of NOS2 during sepsis may compensate for the downregulation of NOS1 and NOS3 with respect to organ perfusion." (PMID 25699985, 2015). "Thus, NOS2 appears to be crucial in hypotension in LPS-induced sepsis." (PMID 23397596, 2013). "A recent study further showed that luteolin (20 mg/kg) inhibits the AKT1/nitric oxide synthase 2/cathepsin G (AKT1/NOS2/CTSG) axis, thereby blocking caspase-11 and GSDMD activation, leading to reduced IL-1β and TNF-α release, thus mitigating sepsis-induced pulmonary injury." (PMID 41394141, 2025). "Among the three isoforms of NOS, NOS2 and NOS3 are more relevant to sepsis." (PMID 38029224, 2023). "Based on these increased plasma nitrite and nitrate levels in septic patients, and on the fact that cytokine-induced NOS2 expression releases more NO during experimental conditions compared to the other NOS enzymes, a key role for NOS2 in the hemodynamic changes of sepsis was expected." (PMID 25699985, 2015). "In addition, NOS‐2 selective inhibitor increased GRK2 levels in the septic kidney, and GRK2 levels of NOS‐2‐KO mice were not reduced during sepsis, thus confirming that NO was indeed involved in the kidney GRK2 disappearance." (PMID 39438268, 2024). "As recently observed in an experimental sepsis model with LPS, excessive NOS2-derived NO production may not be accompanied by hypotension or morbidity during inflammation." (PMID 25699985, 2015). "Also, the identified hub-gene signatures (e.g., NOS2, VEGFa, AKT, HO-1, SOD2) are useful for a deeper understanding of key signaling pathways-connection in sepsis development and may be helpful for early prediction of sepsis progression." (PMID 37407986, 2023). "Also the investigation of a BBS-2, a more potent selective NOS2 inhibitor, was not capable of reversing the sepsis induced vasodilatation, which may indicate that NOS2 may not or only partially be involved in the vasodilatation during sepsis and inflammation." (PMID 25699985, 2015). "When expressed, NOS2 produces much higher levels of NO independent of [Ca2+]i, as compared to the constitutive NOS isoforms, and it is an important mediator in sepsis." (PMID 22482045, 2012).
asthma (53 papers, 2006 to 2025). "One of these polymorphisms (C/T in NOS2 gene) showed a significant association with the risk of asthma in a single marker analysis." (PMID 34946286, 2021). "In our study, we found that NOS2 variant located in the 5′UTR region was associated with childhood asthma in the Polish population." (PMID 34946286, 2021). "Data from CHS also showed that promoter haplotypes in NOS2 had affected respiratory health and were significantly associated with FeNO, asthma incidence and pulmonary function development in school children." (PMID 28821285, 2017). "NOS2 polymorphisms have been investigated in the context of lung function growth and childhood asthma." (PMID 24192154, 2013). "The authors reported associations between allele 3 of the intron 4 (GT)n repeat belonging to NOS2 and both percentage of blood eosinophils and serum nitric oxide levels in 230 families ascertained through asthma." (PMID 22590587, 2012). "One study investigated four microsatellites belonging to NOS2 in families with asthma and reported association between allele 3 of the intron 4 (GT)n repeat and both percentage of blood eosinophils and serum nitric oxide level." (PMID 22590587, 2012). "Similarly, polymorphisms in the iNOS (NOS2) gene affect inflammatory responses and are linked to autoimmune disorders like asthma and Crohn’s disease." (PMID 39940974, 2025). "Present in the respiratory epithelium, NOS2 is strongly linked to exhaled NO levels in asthmatic children and may serve as a redox-related marker of asthma progression." (PMID 40443529, 2025). "Asthma severity also differed for different Ser608Leu exon 16 variants of NOS2 gene." (PMID 37076778, 2023). "This is the first analysis showing that 5′UTR variant in NOS2 gene may be associated with the risk of childhood asthma." (PMID 34946286, 2021). "Using data from the Southern California Children's Health Study (CHS), we previously reported that the two most common promoter haplotypes in NOS2 significantly affects FeNO level in children, and were also associated with asthma risk and lung function growth in children." (PMID 26714306, 2015). "Interestingly, it has recently been reported that gene variants of NOS2 are associated with alteration of NO levels in inflammatory bowel disorders, asthma, atopy, and migraine, all of which are comorbidities shared by IEI." (PMID 25878398, 2015). "NOS2 polymorphisms have been studied in several types of diseases, including malaria, diabetes, rheumatoid arthritis, osteomyelitis and asthma, where NO production has been implicated in the disease pathogenesis." (PMID 20565800, 2010). "Interestingly, it has also recently been reported that gene variants of NOS2 are associated with the alteration of NO levels in inflammatory bowel disorders, asthma, atopy, olfactory dysfunction, and migraine, all of which are comorbidities shared by environmental sensitivity illnesses." (PMID 31881664, 2019). "The joint effects of short-term PM2.5 exposure, NOS2 haplotypes and methylation across the FeNO distribution were significantly larger in the upper tail of the FeNO distribution, with little association in its lower tail, especially among children with asthma and Hispanic white children." (PMID 28821285, 2017). "We further used a one-to-one format for comparison and validated with the GSE63142 dataset The genes CEACAM5, PRR4, CPA3, POSTN, TCN1, CST1 (Cystatin-SN), CLCA1, TPSAB1 and NOS2 (Nitric oxide synthase 2) were highly expressed in patients with asthma." (PMID 39963184, 2025). "PRR4, TCN1, CST1, CLCA1, and NOS2 were also highly expressed in patients with asthma in GSE158752 dataset." (PMID 39963184, 2025). "We report increased NOS2 expression in RV‐A16 infected patients with asthma, as compared to healthy controls." (PMID 39466641, 2025).